DMD (dystrophin)
Diseases named in the same sentence as DMD in open-access papers (continued):
Sharing a sentence is not in itself a finding about the gene and the disease.
genetic disease (100 papers, 2006 to 2026). "DMD is a genetic disorder caused by pathogenic variant mutations in the dystrophin gene, resulting in a deficiency of the dystrophin protein, which is essential for maintaining muscle function." (PMID 40801580, 2025). "This study provides evidence that the EJC plays an important role in regulating splicing in the multi-exon DMD gene encoding the dystrophin protein in skeletal muscle, which causes a major genetic disease in humans when defective." (PMID 38512499, 2024). "AAV vectors are a promising tool in gene therapy for DMD, a genetic disorder caused by mutations in the dystrophin gene." (PMID 39328620, 2024). "DMD is a debilitating genetic disease caused by the loss of dystrophin, a subsarcolemmal protein of the dystrophin–glycoprotein complex that plays a key role in both membrane integrity and mechano-transduction signaling." (PMID 36902405, 2023). "Disturbed regeneration is a hallmark of DMD, a genetic disorder caused by mutations in the structural protein dystrophin, which is also expressed in mSCs." (PMID 36918494, 2023). "Duchenne muscular dystrophy (DMD), caused by various mutations in the Dmd gene, is one of the most common genetic diseases and can reduce the expression of the dystrophin protein." (PMID 36986843, 2023). "Depletion of functional dystrophin protein due to a mutation in the DMD gene causes DMD, a genetic disease leading to muscle weakness and muscle degradation." (PMID 37326971, 2023). "DMD is a genetic disease caused by mutations in the dystrophin-encoding DMD gene on the X chromosome." (PMID 37324396, 2023). "DMD is a genetic disorder caused by mutations in the DMD gene, which encodes a protein necessary for muscle contraction." (PMID 36483767, 2022). "DMD is an intractable genetic disorder caused by loss of the DMD gene, which is composed of 79 exons spanning 2 Mb of the genomic region on the X chromosome, where each exon is flanked by long (mean > 25 kb) introns." (PMID 31811138, 2019). "DMD is a genetic disease caused by deficiency of dystrophin, a critical component of the DGC, acting as a link between cytoskeleton and extracellular matrix in skeletal and cardiac muscles." (PMID 29636844, 2018). "Duchene muscular dystrophy (DMD) is a fatal genetic disease caused by mutations in the DMD gene, leading to dystrophin deficiency." (PMID 24244600, 2013). "Mdx3cv mice are models for DMD, a lethal childhood genetic disease caused by mutations in the dystrophin gene." (PMID 19626133, 2009). "Furthermore, we examine pioneering efforts to engineer circRNAs as therapeutic agents, capable of either neutralizing pathogenic pathways that drive muscle atrophy or restoring dystrophin expression in genetic disease models." (PMID 41322400, 2025). "DMD is a genetic disorder caused by mutations in the dystrophin gene (DMD)." (PMID 35468843, 2022). "DMD is a progressive and lethal genetic disease caused by mutations of the dystrophin gene." (PMID 35978142, 2022). "DMD is caused by a mutation in the X-linked dystrophin gene; it is a recessive genetic disease characterised by alterations in the neuromuscular system, and metabolic and structural disorders of the central nervous system (CNS), which cause mental retardation and metabolic damage." (PMID 24244600, 2013). "Therefore DMD has emerged as a model genetic disorder for understanding and overcoming the challenges associated with developing personalised genetic medicines." (PMID 23984357, 2013). "MD is a genetic disease caused by mutations in dystrophin inducing muscle fiber damage, with resultant muscle necrosis and tissue inflammation, whereas the cause of JIIM is unknown but presumed to result primarily from an autoimmune-mediated destruction of myofibers and muscle capillaries." (PMID 26338728, 2015).
genetic disease (continued). "In addition to the diagnostic implications, the investigation of non-coding regions as possibly implicated in the etiopathogenesis of mutations in DMD but also in other genetic disorders, may disclose findings of interest for basic as well as applied research." (PMID 19040728, 2008). "DMD is a genetic disorder caused by more than 7,000 identified mutations in the DMD gene encoding dystrophin proteins." (PMID 40490752, 2025). "Dystrophin is one of the larger proteins expressed by human cells and is involved in the pathogenesis of one of the most common genetic disorders." (PMID 40493400, 2025). "It should be noted that even partial restoration of functional proteins (e.g., 20–30% of normal dystrophin levels in DMD patients) can provide therapeutic benefits in many genetic diseases." (PMID 38499809, 2024). "DMD is a fatal genetic disorder characterized by progressive muscle wasting and is caused by mutations in the DMD gene which encodes for dystrophin, an essential protein to maintain muscle integrity." (PMID 33071748, 2020). "DMD is a genetic disorder caused by mutations in the dystrophin gene that result in an absence of a functional dystrophin protein, a protein critical for normal muscle function, stability and signalling (Duanet al., 2021)." (PMID 39649621, 2024). "Furthermore, it is feasible that gene therapy for DMD and most of genetic diseases will be accessible within a decade." (PMID 37759719, 2023). "DMD is a genetic disorder characterized by progressive muscle degeneration and weakness due to the absence of dystrophin from the muscle membrane, causing destabilization and contraction-induced muscle cell damage." (PMID 35208266, 2022). "Moreover, we modified the Cas12a-strip assay to detect DMD as a proof-of-concept for its expandable application in detecting other genetic diseases." (PMID 34068874, 2021). "Indeed, the identification of the dystrophin gene and protein heralded the era of human disease genomics that has dramatically increased our understanding of human genetic disease." (PMID 32608079, 2020). "Therefore DMD has emerged as a model genetic disorder for understanding and overcoming of the challenges of developing personalised genetic medicines." (PMID 23984357, 2013). "DMD is a well-characterized genetic disorder caused by the absence of dystrophin." (PMID 35360042, 2022). "DMD is a genetic disorder in which the transcription of the Dystrophin gene and consequently the translation of the dystrophin protein is interrupted due to deletion mutations, which result in the production of non-functional dystrophin." (PMID 35215334, 2022). "The DMD-SMA assay we developed and adopted in this study can analyze the CNAs of a large number of genomic loci of interest with a short TAT of 48 h, which is tolerable and suitable for the detection of genetic disorders." (PMID 37596438, 2024). "The potential clinical utility and validity of reproductive carrier screening for DMD (within an expanded carrier screening panel of 22 monogenic inherited diseases) has been recognised in a study of 766 couples with no family history of genetic conditions." (PMID 35754057, 2022). "However, many mammalian genes involved in genetic disease, particularly signaling receptors such as FGFR2 (120 kilobases) and structural proteins such as dystrophin are significantly larger than 10 kilobases." (PMID 32013077, 2020). "To the best of our knowledge, we report the first case of a boy with two rare genetic disorders, DBA and DMD, who successfully underwent myeloablative allo-HSCT, which cured his DBA and might have had a positive effect on his DMD." (PMID 21639928, 2011). "The library created by the DMD-SMA probe set had more small fragments (148 bp or smaller), with the main peak located near 228 bp, compared with the quality control for the whole-exome sequencing of genetic diseases that are commonly used in sequencing companies." (PMID 37596438, 2024).
genetic disease (continued). "However, in considering how the method may be applied to the diagnosis of rare genetic diseases, it is important to recognize that each genome studied here had many other SV outside of the DMD locus (data not shown)." (PMID 29070057, 2017).
tumor (64 papers, 2011 to 2026). "The most abundant DMD transcript, Dp71ab, mirrored total DMD trends, distinguishing two tumour groups with opposing survival associations." (PMID 40832923, 2026). "Based on our findings here and the literature, we additionally theorise that DMD is more frequently mutated and/or downregulated in aggressive tumours." (PMID 40832923, 2026). "In primary tumors, mutations in the DMD gene contribute significantly to tumor progression due to the loss of dystrophin expression." (PMID 41590495, 2025). "This remains an important question given the potential prognostic utility and improved risk stratification across multiple tumours and the drug target potential of DMD gene products such as Dp71." (PMID 40155657, 2025). "We also examined the association of DMD gene expression with the onset and survival endpoints in tumor patients." (PMID 36900171, 2023). "As Dp71 is the isoform most widely expressed across the body and its splice variants were among the top highly expressed DMD transcripts in tumor and control tissues, we also compared expression patterns of this transcript." (PMID 36900171, 2023). "One patient showed no pathogenic or likely pathogenic somatic mutations by WES on primary tumor and acquired a single deletion of 30Kb in dystrophin (DMD)." (PMID 37730754, 2023). "We further investigated the association between DMD expression and mutations using data from 921 tumor cell lines (cBioPortal)." (PMID 36900171, 2023). "In the low DMD group, 3.01% of tumor samples (61 out of 2025) had DMD NCR mutations compared to 1.09% of samples (22 out of 2025) in the high DMD group." (PMID 36900171, 2023). "While no causation can be confirmed at this stage, it is important to note that DMD dysregulation was associated with specific transcriptomic changes across 15 primary tumors and 140 various tumor cell lines." (PMID 36900171, 2023). "Here, we comprehensively review the overlooked, but accumulating evidence supporting a role for the DMD gene and its variants in neoplastic disease." (PMID 33188621, 2021). "Western blotting and immunohistochemistry on patient tissues harbouring DMD deletions confirmed a loss or reduction of Dp427 protein expression, and electron microscopy revealed a reduced density of cytoskeleton filaments in tumour cells." (PMID 33188621, 2021). "More tumor infiltrating cells were associated with DMD somatic copy-number alterations in LUSC than in LUAD." (PMID 34945000, 2021). "DMD, the gene encoding dystrophin, connects the cytoskeleton with the extracellular matrix and somatic loss has been associated with a tumor suppressor function in several human cancers." (PMID 31341965, 2019). "Recently, DMD has emerged as a potential tumor suppressor in several cancers, where deletions were associated with enhanced tumor cell migration, invasion and anchorage-independent growth." (PMID 31341965, 2019). "The analysis of DMD genetic alterations revealed a high frequency of gene mutations, which was similar to other well-known tumor suppressor genes (BRCA1, BRCA2, PTEN, RB1)." (PMID 27391342, 2017). "Combined loss of dystrophin and dysferlin, as well as dystrophin and calpain-3, leads to accelerated tumor formation." (PMID 21533183, 2011). "Previous studies have shown the normal balance of DMD gene products is disrupted in cancer and have linked Dp71 expression to tumorigenesis, but the findings are conflicting, with some suggesting it is oncogenic and others indicating a tumour‐suppressive role." (PMID 40832923, 2026). "Conversely, in the DMD‐oncogenic group, the association of high DMD with pathways promoting dynamic cellular remodelling and motility suggests that these tumours might be less reliant on ECM stability and thus may be inherently less invasive." (PMID 40832923, 2026). "Additionally, the higher frequency of DMD mutations in this group suggests a selective pressure for DMD loss in aggressive cancers, reinforcing its tumour‐suppressive role." (PMID 40832923, 2026).
tumor (continued). "Since we confirmed the expression of dystrophin protein within HNSCC tumour tissue, we next sought to determine whether low dystrophin protein expression was linked to poor survival as was observed with the TCGA RNAseq dataset above." (PMID 40155657, 2025). "Importantly, we found that reduced DMD expression across different tumors was associated with reduced patients’ survival and higher tumor stage." (PMID 36900171, 2023). "However, only 23% of tumor cell lines with low DMD gene expression (63 out of 276) had DMD mutations, but the majority of cell lines (213 out of 276) had low levels of DMD expression without any detectable mutations." (PMID 36900171, 2023). "Moreover, DMD downregulation affects cell proliferation, adhesion, migration, and invasion —traits that are commonly associated with tumor development." (PMID 36900171, 2023). "We found DMD expression to be associated with the tumor stage." (PMID 36900171, 2023). "In this review, we summarise the tumours in which DMD is implicated and provide a hypothesis for possible mechanisms of tumorigenesis, although the question of cause or effect may remain." (PMID 33188621, 2021). "The first indication that the DGC might play a role in RMS was the high frequency of this type of tumor in mice deficient for α-sarcoglycan and dystrophin, two central components of the DGC." (PMID 31054580, 2019). "Based on the spontaneous occurrence of skeletal muscle-tumors in mice deficient for the so far molecularly unrelated genes dystrophin and dysferlin, we hypothesized that MD-genes in more general might act as tumor suppressors." (PMID 21533183, 2011). "Indeed we observed the spontaneous occurrence of skeletal muscle-tumors also in these mdx-mice, underlining a strain-independent tumor-suppressor role of dystrophin." (PMID 21533183, 2011). "To investigate whether other DAPC genes exhibit similar prognostic patterns to DMD/Dp71ab, we adopted a candidate approach by profiling the hazard ratios for 14 additional DAPC genes across the nine tumour types with significant DMD‐associated survival differences." (PMID 40832923, 2026). "Moreover, an association of the levels of immune infiltrates with DMD mutation was observed, suggesting that DMD may affect tumour development through abnormal immune processes." (PMID 34945000, 2021). "Our model supports and extends this to show that DMD has both tumour‐suppressive and oncogenic roles, depending on the context." (PMID 40832923, 2026). "Their simulations, in line with our model, suggest that when dystrophin is lost, the tumour destabilises faster, pushing it towards uncontrolled growth, suggesting that dystrophin helps regulate tumour dynamics." (PMID 40832923, 2026). "To resolve this, we conducted a comprehensive global analysis of DMD expression and survival outcomes across 33 tumour types using bulk RNA sequencing data from The Cancer Genome Atlas." (PMID 40832923, 2026). "As the field begins to move towards validating DMD and/or its gene products as therapeutic targets in cancer, it is vital to consider context such as tumour type/subtype, stage, and microenvironment to avoid unintended consequences." (PMID 40832923, 2026). "Conversely, in less aggressive tumours, high DMD expression correlates with poor survival, suggesting an oncogenic role in these settings." (PMID 40832923, 2026). "To address these discrepancies, we conducted a comprehensive bioinformatic analysis of DMD expression and its prognostic significance across 33 tumour types." (PMID 40832923, 2026). "Based on these findings, we propose a unified model in which DMD acts as a tumour suppressor in aggressive cancers but exhibits oncogenic properties in less aggressive cancers." (PMID 40832923, 2026). "For BRCA, LAML, LUAD, PAAD, and UVM, patient overall survival was better in those patients with high total DMD tumour RNA expression." (PMID 40832923, 2026).
tumor (continued). "In aggressive tumours with high metastatic potential, low DMD expression correlates with poor survival, supporting a tumour suppressor function." (PMID 40832923, 2026). "Given the expression of multiple DMD transcripts in various tumour tissues, we next repeated our survival analysis to determine which gene product(s) are most strongly linked to overall survival." (PMID 40832923, 2026). "Since loss of ECM integrity and adhesion is a well‐recognised trigger for increased invasiveness and metastatic spread, we propose that in these tumours, high DMD expression serves as a safeguard, counteracting intrinsic aggressiveness." (PMID 40832923, 2026). "Their bifurcation analyses suggest that, in these tumours, the strength of feedback between dystrophin expression and tumour growth is a critical factor influencing stability." (PMID 40832923, 2026). "Instead, we propose a context‐dependent dual model whereby high DMD expression is tumour suppressive in aggressive cancers and oncogenic in less aggressive tumours." (PMID 40832923, 2026). "Our own prior work in LGG and HNSCC provides immunohistochemical validation, confirming dystrophin protein expression in both the nucleus and cytoplasm of tumour cells." (PMID 40832923, 2026). "This broader perspective integrates both gene product levels and tumour‐specific factors to better explain the dual role of DMD in cancer progression." (PMID 40832923, 2026). "Their model only focuses on tumours where downregulated dystrophin is correlated with reduced survival (i.e., the aggressive tumour group in our model)." (PMID 40832923, 2026). "We propose a context‐dependent model where the Duchenne muscular dystrophy (DMD) gene acts as a tumour suppressor in aggressive tumours and as an oncogene in less aggressive ones." (PMID 40832923, 2026). "DMD downregulation is shown to correlate with age of onset, staging and survival in some tumours but gene expression and survival trends vary across others." (PMID 40832923, 2026). "To characterise dystrophin protein expression in tumour tissue we examined 50 HNSCC tissue sections (comprising a 50:50 split of oral cavity and oropharynx cases)." (PMID 40155657, 2025). "Among the 77 primary tumor samples, DMD (13.33%; p = 0.049) was identified exclusively in primary samples and absent in all metastatic samples." (PMID 41590495, 2025). "al. recently developed a mathematical model to simulate the interactions between dystrophin and components of the tumour micro-environment to predict how changes in dystrophin levels affect tumour growth and progression." (PMID 40155657, 2025). "For instance, the genes DMD and PARK2 are lamina-associated regions with structural changes observed in the germ line in patients, and in tumor cells." (PMID 38898078, 2024). "In contrast to this potential tumor suppressor role of the full-length dystrophin, Dp71 expression was essential for myogenic tumor cell growth." (PMID 36900171, 2023). "In each tumor type, the DEGs between samples at the bottom 33.3% and top 33.3% of DMD expression were identified and used to perform a pathway enrichment analysis." (PMID 36900171, 2023). "According to our data, the RAB3C and dystrophin demonstrated coordinated expression, and the tumor tissues exhibited stronger staining than the adjacent normal tissues." (PMID 36652260, 2023). "Further analysis of these DMD transcripts showed that changes in overall DMD expression levels in two tumor categories were confounded by the opposing dysregulation of Dp427m and Dp71 variants." (PMID 36900171, 2023). "DMD ranked within the top 10% of differentially expressed genes in several tumour versus normal tissue comparisons." (PMID 35217778, 2022). "Multivariate analysis including tumour subtype as a factor revealed that DMD expression remained significant whilst tumour subtype did not (P = 0.005)." (PMID 35217778, 2022).